TNF (tumor necrosis factor)
Diseases named in the same sentence as TNF in open-access papers (continued):
Sharing a sentence is not in itself a finding about the gene and the disease.
skin infection (39 papers, 2005 to 2025). An inflammatory process affecting the skin, caused by bacteria, viruses, parasites, or fungi. "Further, IFN- γ response, TNF- α signaling through NF-κb signaling, and inflammatory response are key mechanisms in the progression of both diseases associated with SA skin infection." (PMID 36076953, 2022). "Skin infections caused by S. aureus are related to the exacerbated production of pro-inflammatory cytokines as a tumor necrosis factor-α (TNF-α) and IL-6." (PMID 36313341, 2022). "TNF-α is strongly associated with the severity of skin infections caused by S. aureus." (PMID 36835350, 2023). "It seems that anti-TNF treatment slightly reinforces S. aureus skin colonization, which might increase the risk of a later skin infection." (PMID 28264025, 2017). "Notably, skin infections are largely caused by the IL-17 and TNF pathways." (PMID 40856949, 2025). "In a Staphylococcus aureus skin infection model, IL-17A/F−/− mice had reduced IL-1α, IL-1β, and TNF-α,39 suggesting that IL-17 regulates these proinflammatory mediators." (PMID 39504049, 2024). "Both methods of metformin and rifampicin combined treatment reduced skin lesions size, skin disease score, TNF-α expression and pathological damage to a greater extent than rifampicin therapy alone by day 26 in a recurrent skin infection." (PMID 38241414, 2024). "We found that TNF−/− mice developed significantly larger skin lesions and higher bacterial burdens than WT mice, suggesting that TNF contributed to host defense against the S. aureus skin infection." (PMID 37327341, 2023). "We next set out to determine the kinetics of TNF expression during the S. aureus skin infection to better understand which BM-derived immune cells contributed to TNF production." (PMID 37327341, 2023). "We adopted a well-known mouse model of skin infection to look at the expression of pro-inflammatory genes TNF and CXCL1 and the transcriptional factors NF-κB and IRF3 after the treatment with poly I:C or the vehicle." (PMID 32824595, 2020). "Upon LTA recognition (e.g., in diseases such as colonization and infection of the skin), the NF-κB signaling pathway is activated, leading to the expression of various pro-inflammatory cytokines (TNF-α and IL-1β)." (PMID 29643997, 2018). "Both CTLA4 Ig and anti-TNF treatment resulted in less severe skin infections and smaller post-infectious hyperpigmentation compared with controls." (PMID 28264025, 2017). "The aim of this study was to examine the differential effects of anti-TNF versus CTLA4 Ig treatment on S. aureus skin infections in mice." (PMID 28264025, 2017). "In summary, our data suggest dual effects of CTLA4 Ig and anti-TNF therapies on S. aureus skin infection." (PMID 28264025, 2017). "This strongly suggests a differential immune response between systemic infection and local skin infection to anti-TNF therapy." (PMID 28264025, 2017). "In this study, we demonstrated that both anti-TNF therapy and CTLA4 Ig treatment significantly decreased the severity of skin infection and caused smaller post-infectious hyperpigmentation compared with controls." (PMID 28264025, 2017). "We investigated the immune-modulatory activity of celecoxib in MRSA skin infection by measuring the levels of the inflammatory cytokines IL-6, TNF-α, IL-1β, and MCP-1 using ELISA." (PMID 26284040, 2015). "We conclude that contemporary invasive M3 GAS has a higher capacity to evade neutrophil and TNF-α responses at skin infection sites and to invade soft tissue than M28 MGAS and that the skin-invading capacity of M3 GAS is maximized by natural CovRS mutations." (PMID 26047469, 2015). "It appears that MGAS315 can substantially evade TNF-α-dependent immune responses in skin infection sites." (PMID 26047469, 2015). "One novel result in this study is that MGAS315 substantially inhibits the production of TNF-α compared with MGAS6180 at skin infection sites." (PMID 26047469, 2015).
skin infection (continued). "For example, TNF-α actively participates in the pathogenesis of skin infections." (PMID 38765679, 2024). "Because we observed increased TNF production in the skin as early as day 1 after infection, we hypothesized that innate immune cells were a source of TNF during the S. aureus skin infection." (PMID 37327341, 2023). "S2) because this corresponded to peak TNF expression during the skin infection." (PMID 37327341, 2023). "Furthermore, ebselen has been shown to exhibit potent anti-inflammatory activity in two rodent models of MRSA skin infection reducing the expression of key cytokines (TNF-α, IL-1β, and IL-6) that impair wound healing." (PMID 33617589, 2021). "Both CTLA4 Ig and anti-TNF therapies attenuate disease severity but may prolong the healing time required for S. aureus skin infections." (PMID 28264025, 2017). "It is unrealistic to use TNF inhibitor in patients with minor skin infections." (PMID 28264025, 2017). "Although a more clinically relevant model (skin infection by abrasion) was used in this study, it remains unclear whether anti-TNF treatment or CTLA4 Ig has any impact on S. aureus invasion through the skin barrier." (PMID 28264025, 2017). "Similarly, studies have shown that both IFN-γ and TNF-α contribute to host resistance against systemic SA infection, and that γδ T cell production of both cytokines controlled SA replication in a mouse skin infection model." (PMID 32343740, 2020). "However, the effects of CTLA4 Ig and anti-TNF treatments on a local S. aureus infection (e.g., skin infection) might differ from their effects on a systemic infection." (PMID 28264025, 2017). "However, most infections occurred during active treatment with TNF-α-blocking therapy, a finding that could suggest at least a relative contribution to an increased vulnerability to skin infections in the study population." (PMID 15899052, 2005). "Because both TNFR1 and TNFR2 were crucial for host defense, we next elucidated which cell types respond to TNF via TNFR1 and TNFR2 during the S. aureus skin infection." (PMID 37327341, 2023). "In C. albicans infection, the cytokines IL-6, TNF-α, interleukin-12 (IL-12), interferon-γ (IFN-γ) and interleukin-17 (IL-17) appear in the initial stage of skin infection." (PMID 35053737, 2022). "Skin infections and eczemas are the second most cited cutaneous side effects in pediatric IBD patients treated with anti-TNF agents." (PMID 32842528, 2020). "Corroborating in vitro data, Myd88−/− knockout mice downregulated TNF, CXCL1; and phospho-p65 and phospho-IRF3 nuclear localization, upon poly I:C treatment in a mouse model of skin infection." (PMID 32824595, 2020). "More recently, MG extract is shown to possess antibacterial activity against S. aureus and dramatically downregulate the expression of TH1 cytokines, namely TNF-α, IL-6, and IL-1β, via the TLR-2 pathway in a skin infection model of mice." (PMID 30959963, 2019). "Proinflammatory cytokines and chemokines, such as IL-1α, IL-6, TNFα, and CXCL8, secreted by various cell types play a fundamental role in attracting neutrophils and T cells to the place of skin infection." (PMID 21619700, 2011). "Herein, we found that TNF had a crucial host defense role against S. aureus in the skin, with neutrophils as both a major TNF-producing cell and a predominant TNFR1- and TNFR2-expressing cell during the S. aureus skin infection." (PMID 37327341, 2023). "The results showed that DPTM could promote the healing of MRSA skin infection, reduce the bacterial burden of infected skin MRSA and decrease the secretion of IL-6 and TNF-α inflammatory cytokines in plasma." (PMID 34071703, 2021). "Our data suggest that in contrast to S. aureus systemic infection, S. aureus skin infection is not aggravated by anti-TNF therapy." (PMID 28264025, 2017). "On the one hand, both CTLA4 Ig and anti-TNF therapies attenuate the severity of S. aureus skin infections and have no impact on bacterial clearance in skin tissues." (PMID 28264025, 2017).
skin infection (continued). "Infections of the skin have not been the subject of report in clinical trials and observational studies with TNF-α-blocking therapy." (PMID 15899052, 2005). "Levels of the proinflammatory cytokines IL-1, IL-6, and TNF-α were elevated during wound healing, consistent with previously reported results showing elevated IL-1, IL-6, IL-10, TNF-α, IL-2, IL-8, IL-13 and granulocyte colony-stimulating factor (G-CSF) in the skin infection wound model." (PMID 36901790, 2023). "However, the TNF/TNFR-mediated mechanisms of host defense against S. aureus skin infections are not entirely understood." (PMID 37327341, 2023). "One mouse treated with anti-TNF never developed any sign of skin infections." (PMID 28264025, 2017). "Interestingly, both anti-TNF (p<0.001) and CTLA4 Ig (p<0.01) treatments significantly decreased the size of skin hyperpigmentation on day 18 after skin infections, strongly suggesting that both TNF-alpha and T-cell activation are responsible for post-inflammatory hyperpigmentation." (PMID 28264025, 2017). "The prevalence of SSSTI we identified was lower than rates reported by other studies of anti-TNF drug use and all serious infections in RA patients, however, many of the studies evaluated all skin infections, rather than limiting to serious infections that result in hospitalization." (PMID 24498926, 2013). "However, the role of TNF in the protection against S. aureus skin infections is not well defined." (PMID 37327341, 2023). "Our data demonstrate that both anti-TNF and CTLA4 Ig treatment attenuate the severity of S. aureus skin infection without affecting host bacterial clearance." (PMID 28264025, 2017). "Neither kidney abscesses nor bacterial growth from kidney homogenates was found, suggesting that anti-TNF and CTLA4 Ig do not facilitate the systemic spread of bacteria from a local skin infection." (PMID 28264025, 2017).
squamous cell carcinoma (39 papers, 2012 to 2026). A carcinoma arising from squamous epithelial cells. "The role of TNF-α gene mutations in the risk of squamous cell carcinoma (SCC) remains inconclusive." (PMID 28881857, 2017). "PDPN expression can also be induced by interferon-γ (IFN-γ), transforming growth factor-β (TGF-β), and tumor necrosis factor-α (TNF-α) in squamous cell carcinoma cell lines." (PMID 40741180, 2024). "AP-1 activated by docetaxel appears to target Gadd153/CHOP in gastric cancer cells and that activated by VBL appears to target Fas-L, TNF-α, and Bak in epidermoid carcinoma cells." (PMID 38473345, 2024). "Aggressive squamous cell carcinomas have been reported with JAKi, with older age, previous NMSC, and prior anti-TNF failure associated with increased NMSC risk." (PMID 37724470, 2023). "Further, in the abnormal hyperplasia stage group, the targets of DEmiRNAs were mainly enriched in the TNF, autophagy, and lysine degradation signaling pathway compared to those in the squamous cell carcinoma stage group." (PMID 36800936, 2023). "Inhibition of NF-κB in the mouse epidermis disturbs skin homeostasis and triggers TNF-dependent skin inflammation, epidermal hyperplasia, and subsequent development of squamous cell carcinoma." (PMID 35740272, 2022). "Since the presence of keratin pearls is important in the histologic diagnosis of squamous cell carcinoma, our data indicate that chronic TNFα exposure increases the in vivo growth capacity of HOK-16B cells." (PMID 31911577, 2020). "Recent studies showed that tumor necrosis factor (TNF)-like weak inducer of apoptosis (TWEAK) induces the proliferation of squamous cell carcinoma (SCC) cells." (PMID 32351884, 2020). "In conclusion, EGFR signaling in squamous cell carcinoma cells from the head and neck represses the production of several IFNγ/TNFα-induced T-cell attracting chemokines." (PMID 30192802, 2018). "Previous studies in vitro with human cells and squamous cell carcinoma showed that the concentration of certain pro-inflammatory cytokines and pro-angiogenic cytokines, such as TNF-α, IL-1, IL-6 and IL-8, are increased." (PMID 26905729, 2016). "From oral leukoplakia to squamous cell carcinoma, TNF signaling was upregulated, consistent with ELISA results showing progressive increases in IL-6, IL-8, and GROα/CXCL1 in rat serum, indicating the critical role of the inflammatory microenvironment in carcinogenesis." (PMID 41415031, 2025). "Thus, the EGFR-mediated suppression of IFNγ/TNFα induced chemokine expression in squamous cell carcinoma cells from the head and neck primarily is mediated by both the MEK and JNK signaling pathways." (PMID 30192802, 2018). "In this study, we confirmed that inflammatory factor TNF-α could enhance fusion between squamous cell carcinoma cells 9 (SCC-9) and human umbilical vein endothelial cells (HUVEC)." (PMID 28112190, 2017). "In a recent population-based cohort study conducted in Sweden, the risk of squamous cell cancer (SCC) and basal cell cancer (BCC) was evaluated in patients with RA naïve to biologic drugs, in patients starting TNF inhibitors treatment, and in the general population." (PMID 27630714, 2016). "In squamous cell carcinoma cell lines, chemerin activates STAT-3 signaling, increasing production of IL-6 and TNF-α, leading to infiltration of neutrophils promoting tumor growth." (PMID 40299651, 2025). "In the simple hyperplasia stage group, the targets of DEmiRNAs were mainly enriched in the TNF signaling pathway, autophagy, and the MAPK signaling pathway compared to those in the squamous cell carcinoma stage group." (PMID 36800936, 2023). "Similarly, AP-1 activation and dimerization with c-Jun and Fra-1 were observed in epidermoid carcinoma cells upon VBL treatment, suggesting that Fas L, TNF-α, Bak, insulin-like growth factor binding protein 4, and glutathione s-transferase 3 are target genes." (PMID 38473345, 2024).
squamous cell carcinoma (continued). "Therefore, the primary objective of this study was to investigate the potential utility of TNF-α as a biomarker for assessing different stages of OSMF and histological grades of squamous cell carcinoma (SCC)." (PMID 38595736, 2024). "Hence the present study was done to investigate if TNF α can be used as a biomarker in the assessment of various stages of OSMF and histological grades of squamous cell carcinoma." (PMID 38595736, 2024). "Moreover, we detected human lung pathological samples and found that TNF-α, NF-кB and COX-2 were up-regulated in adenocarcinoma and squamous cell carcinoma than normal ones." (PMID 26318035, 2015). "Initial proteomic analysis of the secretome of two NSCLC subtypes, A549 (adenocarcinoma) and SK-MES-1 (squamous cell carcinoma), detected several secreted proteins with a potential role in tumour development or metastasis i.e. CC, CL, IGFBP-7, VEGF-A and TNF-α." (PMID 26407999, 2015). "In addition, numerous case reports have provided evidence suggesting a potential association between the utilization of TNF-α inhibitors and a higher occurrence of non-melanoma skin cancer (NMSC), specifically squamous cell carcinoma." (PMID 39064094, 2024). "Gingival fibroblasts and the oral human squamous carcinoma cell line HSC‐2 were exposed to interleukin (IL)1β and tumor necrosis factor (TNF)α with and without UDCA." (PMID 31960968, 2020).
adenoma (38 papers, 2008 to 2025). A neoplasm arising from the epithelium. "Genes in cluster 4, which were upregulated during adenoma to carcinoma transition, were mainly involved in canonical pathways associated with cancer, including the TNF, Toll-like receptor, Ras, MAPK, and Hippo signaling pathways, among others." (PMID 34458146, 2021). "We analyzed the associations of circulating levels and single nucleotide polymorphisms (SNPs) of IL-6 and TNF-α with risk of colon adenomas in a colonoscopy -based case-control study of 401 incident adenoma cases and 1,050 controls." (PMID 24235998, 2013). "We have previously shown that elevated levels of plasma IL-6 and TNF-α are associated with increased risk of adenomas." (PMID 23442743, 2013). "In addition, recent data suggest that individuals with chronic, low levels of inflammation (such as increased circulating IL-6 and TNFα) have increased odds of having adenoma and thus increased CRC risk." (PMID 20500855, 2010). "Furthermore, this research suggests that high serum concentrations of leptin (>9 ng/ml), IP-10 (>362.6 pg/ml) and TNF-α (>5.9 pg/ml) could also be used to identify individuals at increased risk for colorectal polyp formation and presence of adenoma." (PMID 24465801, 2014). "Transcriptomic analysis identified upregulation of the expression of E2F targets, KRAS and TNF-alpha signaling, and epithelial-mesenchymal transition pathways in carcinomas compared to adenomas and normal tissues." (PMID 37121965, 2023). "On the contrary to CRC, those immune-related signaling pathways (TNF-α signaling via NF-κB, interferon α/γ responses, and allograft rejection) were significantly upregulated in both polyp or adenoma patients." (PMID 35236405, 2022). "With the exception of TNF-α, clusters 3 & 4 suggest that tumor cells in progressed adenomas exist within a predominantly immunosuppressive niche, with low CD8 T cell infiltration (note the negative spatial association between CD8 and CK)." (PMID 35379804, 2022). "Going back to the data, we then quantified the ratio of immunosuppressive cytokines (TGF-β, IL-10) to inflammatory cytokines (TNF-α) in benign and progressed adenomas." (PMID 35379804, 2022). "In human CRCs, the Mir34aΔIEC adenoma gene signature was associated with EMT, inflammation and actin cytoskeleton signatures, as well as with the TNFα/NFKB, IL6/STAT3 and MAPK signaling pathways." (PMID 36147476, 2022). "Our results showed significant differences in levels of serum adiponectin, IGF-1, and TNF-α in case (adenoma) and control groups (healthy normal)." (PMID 29593647, 2018). "Serum concentrations of adiponectin (pg/ml), IGF-1 (ng/ml), TNF-α (pg/ml), and leptin (pg/ml) were significantly higher in adenoma group." (PMID 29593647, 2018). "In the present study, DMH control animals showed initiation of ACF, promotion into adenoma, and the significant increase in inflammatory mediator (TNF-α and IL-6) levels." (PMID 24995310, 2014). "Specifically, we assessed mRNA expression of mucosal inflammatory cytokines IL-6, IL-10, IL-12, IL-17 and TNF-α in normal rectal biopsies and correlated their expression levels with abundance of Fusobacterium species in adenoma and non-adenoma subjects." (PMID 23335968, 2013). "Only plasma TNF-α levels showed a trend toward being higher in adenoma cases than controls (p=0.06)." (PMID 23442743, 2013). "In fact in healthy subjects, the sIL-2R in men and sIL-6R in women were principally related to IFNγ, which plays an important role in the development of Th1 cells; in adenoma the TNFα in men and IL-4 in women were, respectively, related to IFNγ and IL-6." (PMID 22235223, 2011). "Similarly, our systematic review showed that Th1 cytokines (L-12A, IL-18, IFN-γ, and TNF-α) are upregulated in CR adenomas but turn downwards in CRC tissues." (PMID 40149674, 2025). "Since the expression of TNF-α is significantly higher in serrated adenomas compared to adenomas, its role in the alternative pathway may be more important." (PMID 35884974, 2022).